GABRA6 (gamma-aminobutyric acid type A receptor subunit alpha6)
Diseases named in the same sentence as GABRA6 in open-access papers:
GABRA6 is named in the same sentence as 34 diseases in open-access papers, as found by Europe PMC text mining. Sharing a sentence is not in itself a finding about the gene and the disease. The quoted sentences say what the papers report.
Anxiety (10 papers, 2011 to 2025). Intense feelings of nervousness, tension, or panic often arise in response to interpersonal stresses. "A possible involvement of α6GABAARs in these disorders is also supported by genetic studies investigating GABRA6 variants in epilepsy, stress, anxiety, panic, and mood disorders, as well as by post mortem changes of α6GABAAR expression in these disorders." (PMID 38283799, 2024). "Altered expression of Gabrr2, Gabra6 and Gabra2 is implicated in the pathogenesis of anxiety and depression." (PMID 34448534, 2021). "Thus, the aim of the present study was to investigate the effect of the interaction between different types of recent life events and GABRA6 or CNR1 gene variants on recent depressive/anxiety symptoms in a large European general population sample." (PMID 31024264, 2019). "In our study we demonstrated that genetic variation in two distinct neurochemical systems, namely, rs7766029 in the CNR1 and rs3219151 in GABRA6, mediate the effects of different types of recent stress in depression or anxiety." (PMID 31024264, 2019). "In contrast, GABRA6 rs3219151 showed a significant interaction with social network related life events in case of anxiety and with illness/personal problem-related life events in case of depression." (PMID 31024264, 2019). "In our present study we observed that GABRA6 rs3219151 mediated the effects of different types of life events in the background of depression and anxiety." (PMID 31024264, 2019). "The genes CCK, POMC, MCHR1, GABRA6, HTR2A and DRD2, which associated with heat score in at least one brain area, are known to modulate emotional states like anxiety and satiety or even sexual motivation." (PMID 21504592, 2011). "In our present study we demonstrated that variants in GABRA6 and CNR1 genes, previously implicated in both stress and depression, interact with particular types of recent life stressors in influencing depression and anxiety." (PMID 31024264, 2019). "In a recent study we found that while the T allele of GABRA6 rs3219151 was not directly associated with either depression or anxiety, a strong effect was observed in interaction with recent life stress on both anxiety and depression." (PMID 31024264, 2019). "Interactions of number of recent negative life events and CNR1 (rs7766029) or GABRA6 (rs3219151) polymorphisms on BSI anxiety and BSI depression scores as the outcome in the combined Budapest + Manchester sample." (PMID 31024264, 2019). "However, GABRA6 rs3219151 exerts a significant interaction with RLE-social on BSI anxiety score, and with RLE-illness/personal on BSI depression score." (PMID 31024264, 2019). "Our present results indicating increased maladaptive psychological responses including depression and anxiety symptoms following stress exposure in GABRA6 T carriers support and extend findings that this genetic variant may mediate the effects of stress." (PMID 29018204, 2017). "Furthermore, in case of GABRA6 rs3219151 we also observed that different types of recent stressors contribute to the emergence of different types of psychopathology: depress ion in case of illness and personal concerns and anxiety in case of social network-related problems." (PMID 31024264, 2019). "In the present study we investigated the interaction of GABRA6 rs3219151 and CNR1 rs7766029 in interaction with different types of recent life events on the presence of depression and anxiety in a large general population sample." (PMID 31024264, 2019). "Specifically, in case of anxiety CNR1 rs7766029 showed an interaction with recent financial stress and GABRA6 rs3219151 with recent social network-related stressors." (PMID 31024264, 2019). "In our present study effect of rs3219151 of GABRA6 gene in interaction with recent negative life events on lifetime and current depression, current anxiety, as well as lifetime suicide were investigated using regression models in a white European general sample of 2283 subjects." (PMID 29018204, 2017).
depression (9 papers, 2011 to 2025). "Our results concerning the association of the GABRA6 T allele in interaction with the environment on current and, to a limited extent, lifetime depression are in line with and in support of these previous findings." (PMID 29018204, 2017). "In case of depression, CNR1 rs7766029 similarly interacted with recent financial stress, GABRA6 rs3219151, however, interacted with recent illness and personal problem stressors." (PMID 31024264, 2019). "Nevertheless, GABRA6 rs3219151 has shown a gene-environment correlation with RLE-illness/personal in Budapest, albeit with the opposite direction of effect compared to that of the GxE on BSI depression." (PMID 31024264, 2019).
epilepsy (5 papers, 2016 to 2024). A brain disorder characterized by episodes of abnormally increased neuronal discharge resulting in transient episodes of sensory or motor neurological dysfunction, or psychic dysfunction. "For the GABRA6 rs3219151 polymorphism, four studies were included involving 1,299 patients with epilepsy and 929 controls." (PMID 36188399, 2022). "We aimed to assess the association of GABRA1 rs2279020 and GABRA6 rs3219151 with epilepsy risk using a meta-analysis." (PMID 36188399, 2022). "For instance, a variety of genetic studies indicate an association of GABRA6 variants and neuropsychiatric phenotypes, such as epilepsy, stress disorder, anxiety disorder, major depression, panic disorder, bipolar disorder, schizophrenia, or alcohol-associated disorder." (PMID 38283799, 2024). "Meta-analysis of GABRA1 rs2279020 and GABRA6 rs3219151 polymorphisms with the risk of epilepsy." (PMID 36188399, 2022). "Moreover, the relationship between rs3219151 polymorphism in GABRA6 and the susceptibility of epilepsy is also evaluated in this meta-analysis." (PMID 36188399, 2022). "We found that neither the GABRA1 rs2279020 nor the GABRA6 rs3219151 polymorphism was a risk factor for the etiology of epilepsy and antiepileptic drug responsiveness." (PMID 36188399, 2022). "In conclusion, the present accumulated evidence revealed that neither the GABRA1 rs2279020 nor the GABRA6 rs3219151 polymorphism was a risk factor for the etiology of epilepsy and antiepileptic drug responsiveness in the Asian and Arabic populations." (PMID 36188399, 2022). "This meta-analysis suggests that GABRA1 rs2279020 and GABRA6 rs3219151 are not risk factors for the etiology of epilepsy and antiepileptic drug responsiveness in the Asian and Arabic populations." (PMID 36188399, 2022). "Meta-analysis of GABRA1 rs2279020 and GABRA6 rs3219151polymorphisms with drug-resistance epilepsy." (PMID 36188399, 2022). "The GABRA6 (Gamma-Aminobutyric Acid Type A Receptor Alpha6 Subunit) mutation V269I (n = 1 WHO°I IVM) is associated with epilepsy, but, until now, has not been linked to cancer." (PMID 31470906, 2019). "We found that variants in the epilepsy-associated genes GABRA1, GABRB3 and GABRG2 were mainly present in the ESP variants, but the GEC cohort contained epilepsy-associated GABRA6, GABRB1, and GABRB2 and non-epilepsy- associated GABRA4, GABRA5, and GABRG3 genes." (PMID 27622563, 2016).
idiopathic generalized epilepsy (4 papers, 2019 to 2025). A generalised epilepsy that encompasses several common seizure phenotypes including childhood absence epilepsy, juvenile absence epilepsy, juvenile myoclonic epilepsy and epilepsy with generalized tonic-clonic seizures alone. "Current research mainly focuses on Gabra6 polymorphisms as significant risk factors for idiopathic generalized epilepsy, with limited exploration of Gabra6 in PTSD progression." (PMID 39665190, 2025). "Polymorphisms encoded by GABRA6 are important risk factors for the development of idiopathic generalized epilepsy and a case of Dravet syndrome associated with GABRA6 (Glu218Ala) mutation has been reported." (PMID 39665190, 2025). "Mutations in Gabra6 have also been identified in patients with idiopathic generalized epilepsy, and its single-nucleotide polymorphism is associated with schizophrenia." (PMID 37545878, 2023). "Previous studies have shown that mutations of the GABA receptors, such as, GABRA1, GABRA5, GABRA6, GABRB3, GABRD, GABRG2, were associated with idiopathic generalized epilepsy." (PMID 35663265, 2022).
schizophrenia (3 papers, 2016 to 2025). A major psychotic disorder characterized by abnormalities in the perception or expression of reality. "In a group of schizophrenia patients, rs3219151 (C > T, GABRA6) was identified and related to the decreased risk for schizophrenia." (PMID 27473590, 2016).
Ataxia (2 papers, 2014 to 2024). Ataxia refers to impaired coordination of voluntary muscle movement. "Whether the Gabra6-specific deletion of Ntrk2 would lead to ataxia symptoms has not been previously explored." (PMID 39194574, 2024).
breast carcinoma (2 papers, 2017 to 2025). "Twenty of the 27 common genes have published data presenting that these genes were associated with breast cancer, but seven genes (DUSP10, GABRA6, GABRR1, KIF21B, KLHL24, MAP2K2, and SLC10A1) might be passenger genes or have not yet been studied regarding their pathological roles in breast cancer." (PMID 28973975, 2017).
nicotine addiction (2 papers, 2021 to 2022). "GABRA6 is annotated to multiple enriched pathways, including taste transduction and nicotine addiction, and has been linked to the susceptibility and pathophysiology of the MIA-associated schizophrenia spectrum disorder." (PMID 36672818, 2022).
panic disorder (2 papers, 2017 to 2021). An anxiety disorder characterized by multiple unexpected panic attacks with persistent concern of recurring attacks. "For instance, miR-138-2 (ML cell signature) is associated with panic disorder and directly targets the gamma-aminobutyric acid receptor GABRA6, a gene implicated in the etiology of anxiety disorders." (PMID 35004351, 2021).
behavioral disorders (1 paper, 2024). "Thus, the understanding of how Jdp2 controls the cell cycle and the differentiation of Gabra6+ GCPs into functional PCs through calcium uptake is critical for the development of the use of Jdp2 to treat PC-mediated genetic diseases and related behavioral disorders." (PMID 39695141, 2024).
developmental and epileptic encephalopathy (1 paper, 2024). An epilepsy associated with developmental impairment that may be due to either the underlying etiology or the superimposed epileptic activity, or both. "Within the cohort of patients experiencing developmental and epileptic encephalopathy (DEE), WES has revealed genetic variants in novel genes (FGF12, GABBR1, GABBR2, ITPA, KAT6A, PTPN23, RHOBTB2, SATB2) and candidate epilepsy-associated genes (CAMTA1, FAT3, GABRA6, HUWE1, PTCHD1)." (PMID 39523358, 2024).
escherichia coli infection (1 paper, 2024). Infection with the organism Escherichia Coli. "Few targeted genes in humans like LCP2, GABRA6, and MYH14 were predicted to be associated with disease pathways of Yesinia infection (hsa05135), neuroactive ligand-receptor interaction (hsa04080), and pathogenic Escherichia coli infection (hsa05130), respectively." (PMID 38674383, 2024).
Intellectual disability (1 paper, 2023). "Conditional, homozygous deletion of Chd4—a chromatin remodeler implicated in intellectual disability and expressed in many cerebellar cell types—in mature granule cells (driven by Gabra6-Cre) caused moderate 3D changes across the mouse genome." (PMID 36865235, 2023).
mental disorder (1 paper, 2022). A disease that has its basis in the disruption of mental process. "The core targets of SHR during the treatment of mental disorders were GABRA1, GABRA2, GABRA3, GABRA5, and GABRA6, involving synaptic transmission and transmembrane movement." (PMID 39280954, 2022).
Osteochondrosis (1 paper, 2025). Abnormal growth ossification centers in children. "In the present study, among the genes nearby the associated SNP on chromosome 14, the genes GABRA1, GABRB2 and, especially, GABRA6 have previously been suggested to be associated with osteochondrosis in Standardbreds, and Hanoverian warmblood horses (GABRA6) (Naccache, Metzger, and Distl 2018)." (PMID 39754479, 2025).
serous ovarian cancers (1 paper, 2014). "In addition, this panel is targeting “hotspot” region of genes that are frequently mutated in human cancer thus other infrequently altered genes but of significance to serous ovarian cancers might have been excluded such as ARID1A, BRCA1, BRCA2, CSMD3, NF1, CDK12, FAT3 and GABRA6." (PMID 25404506, 2014).
cancer (3 papers, 2014 to 2024). A tumor composed of atypical neoplastic, often pleomorphic cells that invade other tissues. "The frequency of mutation in the GABRA6, GABRA1, and GABRB2 genes was significantly higher than that detected for other cell-cycle- and cell-proliferation-related genes; furthermore, their co-occurrence in patients with cancer was examined." (PMID 39695141, 2024). "The GABRA6 mutation is associated with childhood absence epilepsy but, to date, has not been linked to cancer." (PMID 31470906, 2019).
infection (1 paper, 2013). The state of being infected such as from the introduction of a foreign agent such as serum, vaccine, antigenic substance or organism. "Consistent with our previous findings, expression of both GABRA6 and CDK5 was decreased following infection with MCMV when compared to control mice." (PMID 23505367, 2013).
GABRA6 also shares sentences with these, for which no sentence is quoted: mood disorder (2 papers); ovarian carcinoma (2); anxiety disorder (1); arrhythmogenic right ventricular cardiomyopathy (1); brain tumors (1); Dravet syndrome (1); dyspraxia (1); Epileptic encephalopathy (1); genetic diseases (1); insomnia (1); movement disorder (1); myopia (1); non-small cell lung carcinoma (1); Obesity (1); tumor (1); viral infection (1).